SMAD2 (SMAD family member 2)
Diseases named in the same sentence as SMAD2 in open-access papers (continued):
Sharing a sentence is not in itself a finding about the gene and the disease.
pulmonary fibrosis (continued). "In bleomycin-induced pulmonary fibrosis, the ATF4-responsive lnc949 alleviates fibrotic remodeling by modulating TGF-β/Smad2/3 and JNK pathways, thus reducing Epithelial–Mesenchymal Transition (EMT) and collagen deposition." (PMID 40777108, 2025). "KCNN4 promotes Smad2/3 signaling in IPF-derived fibroblasts, facilitating the differentiation of fibroblasts into myofibroblasts and promoting the formation of pulmonary fibrosis." (PMID 40149666, 2025). "Heterophyllin B inhibited TGF-β1 and Smad2/3 phosphorylation, and reduced myofibroblast markers α-SMA and COL-1 in lung tissues, demonstrating anti-pulmonary fibrosis effects." (PMID 40438605, 2025). "In idiopathic pulmonary fibrosis, GPX4 levels in pulmonary fibroblasts are reduced, and GPX4 knockdown significantly enhances TGF-β-induced SMAD2/3 activation, thereby promoting myofibroblast differentiation in lung fibroblasts." (PMID 40001138, 2025). "Deletion of Nedd4–2 leads to ubiquitination and phosphorylation of Smad2/3, resulting in dysregulation of TGF-β signaling and impaired mucociliary clearance, thereby affecting pulmonary fibrosis." (PMID 40901482, 2025). "Mangiferin reduced BLM‐induced inflammation and pulmonary fibrosis by inhibiting the TLR4/p65 pathway and the EMT process through interruption of the TGF‐β1/Smad2/3 pathway in mice." (PMID 40783911, 2025). "The TGF-β1 signaling pathway significantly affects the regulation of fibroblast activation, in which the key proteins Smad2 and Smad3 are the main downstream regulators that promote TGF-β1-mediated lung fibrosis." (PMID 38895626, 2024). "The phosphorylation of Smad2 modulates collagen secretion, proliferation, and transformation and the excessive deposition of ECM in fibroblasts during pulmonary fibrosis." (PMID 39125585, 2024). "Research findings from both in vitro and in vivo settings indicate that M-siTGF-β1 attenuates the pronounced expression of p-Smad2/3 in cells and tissues afflicted with BLM-induced pulmonary fibrosis." (PMID 39044233, 2024). "In an in vivo silica inhalation-induced model of pulmonary fibrosis, Sirt1 expression was increased following treatment with emodin, which led to Smad3 deacetylation and inhibition of TGF-B/Smad2/3 signaling." (PMID 38474385, 2024). "Because TGF-β1 is one of the most potent activators of lung fibrosis, we determined that derrone inhibits the TGF-β-dependent Smad signaling pathway using SBE-luciferase activity and phosphorylation of Smad2 and Smad3." (PMID 37108428, 2023). "After TGF-β1 stimulation of cells, Smad2/3 and Smad4 aggregated to form protein complexes that entered the nucleus and thus promoted ECM production and aggravated pulmonary fibrosis." (PMID 37416778, 2023). "Mefunidone was shown to reduce the expression of Snail and vimentin by inhibiting the transduction of the TGF-β/Smad2 signaling pathway and the activation of the MAPK pathway, thereby inhibiting the process of EMT and improving pulmonary fibrosis." (PMID 36479180, 2022). "Costunolide (COS) contains a MAM structure and can alleviate pulmonary fibrosis by modulating NF-κB and TGF-β1/Smad2/Nrf2-NOX4 signaling pathways." (PMID 36408214, 2022). "In this study, the gene expression levels of type I collagen, TGF-β1, α-SMA, Smad-2 and MMP-9 were significantly upregulated in the lung tissue of mice with bleomycin-induced pulmonary fibrosis." (PMID 35625905, 2022). "When this miRNA was over-expressed, pulmonary fibrosis induced in bleomycin-mice model was mitigated by targeting α-SMA, and Smad2/4 transcription factors." (PMID 35743055, 2022). "In BLM-induced pulmonary fibrosis mice, BBJ ameliorated the distortion of normal architecture by reducing collagen deposition and inhibiting the TGF-β1/Smad2/3 pathway." (PMID 35418869, 2022). "SMAD2/3 participates in the pulmonary fibrosis pathway, and targeting TGF-β-mediated SMAD2/3 signaling prevents fibrosis." (PMID 34831433, 2021).
pulmonary fibrosis (continued). "Our results found that p-Smad2/3 expression was increased in activated lung fibroblasts induced by TGF-β1 and in lung tissues of bleomycin-induced pulmonary fibrosis." (PMID 34925016, 2021). "Here, we clearly demonstrated that YTH‐60 prevented lung fibrosis by modulating TGF‐β1/Smad pathway in vitro, evidencing by decreasing Erk1/2 and Smad2/3 phosphorylation." (PMID 34121240, 2021). "The extract of Xin Jia Xuan Bai Cheng Qi decoction was found to alleviate a bleomycin-induced model of pulmonary fibrosis in rats by inhibiting TGF-β1 and Smad2 expression, while increasing the activation of Smad7." (PMID 33981353, 2021). "In the bleomycin-induced pulmonary fibrosis model, cytomegalovirus is considered to accelerate existing fibrosis according to enhancing TGFB1 activation and the expression of both phospho-SMAD2 and Vimentin." (PMID 34880861, 2021). "Pulmonary fibrosis-regulatory lncRNA (PFRL) regulates the reciprocal repression of miR-26a and Smad2, which elicits the proliferation of activated epithelial cells, and contributes to the collagen deposition and progression of lung fibrosis." (PMID 34819948, 2021). "In bleomycin-induced pulmonary fibrosis in mice, AGK2 treatment significantly mitigated the degree of fibrosis and decreased the phosphorylation of Smad2/3." (PMID 34925016, 2021). "TGF-β1, CTGF, p-Smad2, Collagen I and Collagen III protein levels in the lung were significantly elevated by PQ-induced pulmonary fibrosis in vivo (p < 0.05)." (PMID 30744607, 2019). "It’s reported that treatment with salidroside can protects against bleomycin-induced pulmonary fibrosis via inhibition of NF-κB and TGF-β1/Smad-2/− 3 pathways." (PMID 29986685, 2018). "In this study, we found that ANP attenuated pulmonary fibrosis and inflammation induced by BLM, at least in part, via inhibition of Smad2 phosphorylation in TGF-β signaling." (PMID 28049526, 2017). "Tgf-β1, Smad2, and Col1α1 mRNA expressions were increased in BLM-induced pulmonary fibrosis, whereas they were decreased after rhBMP3 administration in a dose-dependent manner." (PMID 29113323, 2017). "The molecular evidence revealed for the first time that TGF-β1/Smad2/3 signaling pathway and EMT were suppressed by iPS cell treatment during BLM-mediated pulmonary fibrosis." (PMID 27895584, 2016). "To assess effects of RPE in PQ-induced lung fibrosis, we measured miR-21 and FSTL1 gene expression with real-time PCR and p-p38MAPK, NF-kB65, p-Smad2/3 and MMP-9 protein expression with western blotting in lung tissue from mice on day 14 after PQ challenge." (PMID 26758514, 2016). "Expression levels of miR-21, FSTL1, p-p38MAPK, NF-kB65, p-Smad2/3 and MMP-9 in the lung were increased during PQ-induced pulmonary fibrosis." (PMID 26758514, 2016). "Cav1 modulates SMAD2 and SMAD3 nuclear accumulation in fibroblasts in an experimental model of idiopathic pulmonary fibrosis." (PMID 25550395, 2015). "Taken together, these data provide the evidence that IL-22 regulates the process of BLM-induced EMT and pulmonary fibrosis, likely via TGF-β/Smad2 signaling pathway." (PMID 23476100, 2013). "Further, AG treatment also decreased BLM-induced HSP47 expression, downregulated TGFβ1, p-Smad2 and p-Smad3 expressions, and subsequently attenuated BLM-induced pulmonary fibrosis." (PMID 19552800, 2009). "We hypothesize that LP03 attenuates BLM-induced pulmonary fibrosis through modulation of gut microbiota and elevation of palmitoylethanolamide (PEA), thereby suppressing the TGF-β1/Smad2/3-mediated EMT pathway." (PMID 40994978, 2025). "To determine whether DST-3 modulates pulmonary fibrosis via the TGF/Smad pathway, we first examined the expression of TGF-β receptors and Smad2/3 phosphorylation in MRC5 cells." (PMID 41155944, 2025). "We hypothesized that M-siTGF-β1 could effectively dampen the TGF-β1-mediated activation of the Smad2/3 signaling pathway, thereby mitigating EMT in pulmonary fibrosis." (PMID 39044233, 2024).
pulmonary fibrosis (continued). "Overexpression of TXNIP attenuated transforming growth factor-β1 (TGF-β1)-induced phosphorylation of Smad2/3 and fibronectin expression in lung fibroblasts, suggesting that decrease in TXNIP may contribute to the pathogenesis of lung fibrosis." (PMID 38529321, 2024). "To determine whether CAT played an important role in the TGF-β signaling pathway in pulmonary fibrosis, we measured the protein expression levels of TGF-β1, Smad2/3, p-Smad2, p-Smad3, Smad7 as well as Snail." (PMID 35685407, 2022). "Furthermore, BBJ exerted its anti-lung fibrosis effect by preventing cell migration and TGF-β1/Smad2/3 pathway activation." (PMID 35418869, 2022). "Collectively, these findings demonstrated that CB1R-specific agonist ACPA exhibited antifibrotic efficacy in both in vitro and in vivo models of pulmonary fibrosis, revealing a novel anti-fibrosis approach to fibroblast-selective inhibition of TGF-β-Smad2/3 signaling by targeting CB1R." (PMID 35355726, 2022). "In this study, the results showed that miR-21promotes lung fibrosis, as well as TGFβ1-induced ECM over-synthesis, after binding of TGFβ1 to TGFβ1R1, which activates the SMAD2/3 complex and the nuclear entry of SMAD4, facts that regulate both miR-21 expression and ECM protein expression." (PMID 35743055, 2022). "In summary, our study points out that catalpol is able to inhibit pulmonary fibrosis, and the mechanism may lie in down-regulating Ang II and AT1 as well as inhibiting EMT progression through the TGF-β/Smad2/3 signaling pathway." (PMID 35685407, 2022). "Overall, pretreatment with VPA attenuated the development of pulmonary fibrosis by inhibiting EMT in mice, which was associated with Smad2/3 deactivation but without Akt cellular signal involvement." (PMID 34168289, 2021). "Secondly, this study did not explore the exact mechanism which TUDCA inhibited TGF-β/Smad2/3-mediated EMT in BLM-evoked lung fibrosis." (PMID 33952237, 2021). "Our results suggest that neutralizing IL-9 may alleviate pulmonary fibrosis by regulating the STAT3 and SMAD2/3 pathways." (PMID 34831433, 2021). "Collectively, these findings suggest the possibility that MFD might attenuate pulmonary fibrosis, inhibit cell apoptosis, and suppress EMT via down-regulation of TGF-β/Smad2 and MAPK pathways." (PMID 34630088, 2021). "In vivo, pretreatment with VPA attenuates pulmonary fibrosis development through EMT inhibition in mice, which was associated with Smad2/3 deactivation but without Akt signal involvement." (PMID 34168289, 2021). "Our data demonstrated that MFD could ameliorate BLM-induced pulmonary fibrosis, abate mitochondria-dependent cell apoptosis, and inhibit EMT via suppression of TGF-β/Smad2 and MAPK pathways." (PMID 34630088, 2021). "In summary, we demonstrated that MFD could attenuate BLM-induced lung fibrosis, reduce cell apoptosis and EMT, and suppress TGF-β/Smad2 and phosphorylation of MAPK pathway." (PMID 34630088, 2021). "In pulmonary fibrosis, nagilactone D, a dinorditerpenoid derived from Podocarpus nagi, attenuated the TGF-β1-induced expression of collagen I, collagen III, and fibronectin in human pulmonary fibroblasts and suppressed the phosphorylation of Smad2." (PMID 33981353, 2021). "PFD alleviated pulmonary fibrosis in vitro and in vivo through regulating Wnt/GSK-3β/β-catenin and TGF-β1/Smad2/3 signaling pathways, which might further improve the action mechanism of anti-fibrosis effect of PFD." (PMID 32448163, 2020). "Although ART has been proved to interrupt TGF-β signaling in pulmonary fibrosis models, the mechanism of whether the ART directly inhibit phosphorylation of Smad2/3 (pSmad2/3) in MSCs in ACLT mice needs be further elucidated in the following study." (PMID 31258481, 2019). "Moreover, Cyp27b1 gene knockout aggravated pulmonary TGF-β/Smad2/3 activation and subsequent EMT in BLM-induced lung fibrosis." (PMID 31775746, 2019).
pulmonary fibrosis (continued). "One of the most abundant antifibrotic miRNAs is miR-27a, and lentiviral delivery of miR-27a-3p has been reported to reduce BLM-induced pulmonary fibrosis by targeting the phenotypic marker of myofibroblasts, alpha-smooth muscle actin (α-SMA), and two key Smad transcription factors, Smad2 and Smad4." (PMID 31949877, 2019). "Consequently, neutrophil elastase activates the Smad2/Smad3/α-SMA pathway to induce myofibroblast differentiation and pulmonary fibrosis." (PMID 31905700, 2019). "In addition, Cyp27b1 gene knockout aggravated pulmonary TGF-β/Smad2/3 activation and subsequent EMT during BLM-induced lung fibrosis." (PMID 31775746, 2019). "More importantly, our study provided the first line of evidence supporting the notion that transplantation of iPS cells could suppress TGF-β1/Smad2/3 signaling pathway and EMT during BLM-induced lung fibrosis." (PMID 27895584, 2016). "However, administration of RPE significantly suppressed PQ-induced miR-21 expression, blocked FSTL1 expression, decreased p-p38MAPK, NF-kB65, p-Smad2/3 and MMP-9 protein levels and attenuated pulmonary fibrosis." (PMID 26758514, 2016). "GA treatment inhibited BLM-induced upregulation of α-SMA and also reduced BLM-induced upregulation of TGF-β1 and phosphorylation of Smad2/3, suggesting that GA may mitigate BLM-induced pulmonary fibrosis by inhibiting TGF-β signaling pathway." (PMID 26483688, 2015). "Furthermore, blockage of IL-22 deteriorated pulmonary fibrosis, with elevated EMT marker (α-smooth muscle actin (α-SMA)) and overactivated Smad2." (PMID 23476100, 2013). "In a study of bleomycin (BLM)‐induced pulmonary fibrosis in mice, administration of mangiferin (40 mg/kg) exhibited potential anti‐fibrotic effects by blocking Epithelial‐Mesenchymal Transition (EMT) primarily through inhibition of Smad2/3 phosphorylation and matrix metalloproteinase‐9 (MMP‐9)." (PMID 40783911, 2025). "In other fibrotic diseases, N‐butyldeoxynojirimycin (miglustat), an inhibitor of glucosylceramide synthase (GCS) exerts its therapeutic effect on pulmonary fibrosis through inhibition of nuclear translocation of Smad2/3 rather than through suppression of TGF‐β1‐induced Smad2/3 phosphorylation." (PMID 39866837, 2025). "SMAD4 and SMAD7 have a regulating activity to SMAD2/3 and play a significant regulatory role in pathophysiological processes such as skin healing and pulmonary fibrosis; however, NAM showed no obvious effect on the protein expression of SMAD4 and SMAD7 at 28 dpi." (PMID 38973179, 2024). "Baicalein, one of the flavones in Codium fragile, inhibited pulmonary fibrosis by reducing microRNA-21 levels, which play an important role in the pathogenesis of pulmonary fibrosis, and by suppressing the up-regulated expression levels of TGF-β1 and p-Smad-2/3 in bleomycin-treated rats." (PMID 37760047, 2023). "Furthermore, ELISA was used to detect pulmonary fibrosis markers COL-1, COL-3, WNT, Vimentin, β-Catenin, Fibronectin, α-SMA, N-Cadherin, E-Cadherin, TWIST, CTGF, FGF2, PDGF-α, MMP2, MMP8, MMP9, MMP13, TIMP1, TGF-β, Smad2, and Smad3 expression levels." (PMID 37812357, 2023). "In addition, CC-11050 treatment significantly downregulated the expression of genes that play a key role in lung fibrosis, such as TGFB1 (16 dpi; p=0.0433), COL1A1 (16 dpi, p=0.009), TAGLN (16 dpi; p=0.0218), MYH11 (4 dpi; p=0.0042; 16 dpi; p=0.05) and SMAD2 (16 dpi; p=0.008)." (PMID 37854602, 2023). "However, QLJP inhibited the TGF-β1/Smad2 signaling pathway, down-regulated the expression levels of α-SMA, COL1A1, MMP2, and improved pulmonary fibrosis and pulmonary arteriole remodeling induced by low-temperature exposure to play a role in the prevention and treatment of PAH." (PMID 36611616, 2022). "Our results showed that atorvastatin and ezetimibe could prevent HCD-induced lung fibrosis by downregulating the TGF-β-SMAD2/3 signaling pathway and enhancing MMP-19 expression, but not by modulating pro-fibrotic enzyme action." (PMID 37082028, 2022).
pulmonary fibrosis (continued). "Thus, our findings suggested that MFD could ameliorate lung fibrosis, cell apoptosis and EMT potentially via suppression of TGF-β/Smad2 and MAPK pathways." (PMID 34630088, 2021). "Moreover, c-Abl-kinase was shown to promote TGF-β-induced pulmonary fibrosis independent of Smad2/3 phosphorylation." (PMID 33081058, 2020). "To elucidate the effect of LRG on TGF‐β‐Smad2 signaling in lung fibrosis, we investigated whether the absence of LRG affects TGF‐β production and/or signaling." (PMID 29279415, 2017). "Collectively, our results suggest that transplantation of iPS cells could suppress inflammatory responses, TGF-β1/Smad2/3 pathway and EMT during the progression of BLM-induced pulmonary fibrosis, providing new useful clues regarding the mechanisms of iPS cells in the treatment for this disease." (PMID 27895584, 2016). "Since DA-Raf does not directly affect Smad2/3 signaling but suppresses the TGF-β1-induced non-Smad Ras—ERK pathway, the information obtained in this study might provide ideas to treatment for pulmonary fibrosis without loss of the other important functions of TGF-β1 in maintaining homeostasis." (PMID 25996975, 2015). "As for pulmonary fibrosis, Mig ameliorated pulmonary fibrosis in a BLM-induced lung injury model by inhibiting TGF-β1-induced Smad2/3 nuclear translocation, rather than Smad2/3 phosphorylation." (PMID 39934657, 2025).